KIT (KIT proto-oncogene, receptor tyrosine kinase)
Diseases named in the same sentence as KIT in open-access papers (continued):
Sharing a sentence is not in itself a finding about the gene and the disease.
tumor (continued). "Intraperitoneal or oral administration of masitinib inhibited tumour growth in mice with subcutaneous grafts of Ba/F3 cells expressing the Δ27 KIT mutant." (PMID 19789626, 2009). "When selection of differentially expressed genes was performed according to the discriminating KIT transcript levels, the microarray data from the two groups of 15 and 13 tumour samples with either high or low KIT expression were included in analyses." (PMID 19943934, 2009). "Among 25 tumours that were assessable for c-KIT copy number analysis by FISH, 1 (4%) had evidence of gene amplification and 1 (4%) was polysomic." (PMID 19904263, 2009). "Even though the biological consequences of KIT and PDGFRA mutations seem to be similar, our study has revealed hundreds of differentially expressed genes that group the tumours according to the receptor mutation status and receptor gene expression." (PMID 19943934, 2009). "Of these, 253 probe sets (171 genes) were upregulated, and 427 probe sets (299 genes) were downregulated in tumours with overexpressed KIT compared to those with low expression." (PMID 19943934, 2009). "In vivo, masitinib blocked tumour growth in mice with subcutaneous grafts of Ba/F3 cells expressing a juxtamembrane KIT mutant." (PMID 19789626, 2009). "Specifically, among 12 patients with adequate tumour material available for analysis, 3 had c-KIT polysomy or gene amplification." (PMID 19904263, 2009). "Although mutations in KIT and PDGFRA contribute to tumour development through similar pathways, they correlate with certain clinicopathological features and different responses to imatinib treatment." (PMID 19943934, 2009). "Tumours are often positive for the c-KIT (CD117) protein which is a tyrosine kinase receptor and is the most sensitive and specific marker." (PMID 18501013, 2008). "Among the 38 GIST patients, tumour KIT genotypes of 20 patients were available (corresponding to 111 different plasma samples)." (PMID 18475296, 2008). "Because c-kit tyrosine kinase receptor has an important role in tumor progression, the KIT inhibitor imatinib mesylate is being explored for therapeutic efficacy." (PMID 17044945, 2006). "KIT is a tyrosine kinase receptor expressed by several tumours, which has for specific ligand the stem cell factor (SCF)." (PMID 16570044, 2006). "The heterozygous KIT exon 11 deletions detected in two out of the three tumours, were similarly present in the corresponding primary cultures." (PMID 16570044, 2006). "KIT has, however, also been reported to be expressed in one-third of N-SEMs, reflecting the heterogeneity of these tumours." (PMID 15856041, 2005). "Tumours showing aberrantly high expression of KIT were further tested for KIT amplification by fluorescence in situ hybridisation (FISH)." (PMID 15583695, 2004). "Both KIT and PDGFRA expression were associated with high tumour grade, high proliferation index and poor patient outcome." (PMID 15583695, 2004). "Six of these 10 tumours showed a normal copy number (two signals) for both chromosome 4 centromere probe and the KIT probe." (PMID 15583695, 2004). "When tumours with low and high KIT expression were analysed as one group (positive KIT expression), the difference was statistically significant (P=0.0414)." (PMID 15583695, 2004). "Viable spindle-shaped tumour cells were observed in the solid part by histology, and immunohistochemistry revealed that the tumour cells were KIT-positive." (PMID 15150562, 2004).
tumor (continued). "To investigate further the role of KIT in predisposition to TGCT, and the role of somatic mutations in familial tumours, we have examined a series of constitutional and tumour DNAs from patients with TGCTs and a family history of the disease." (PMID 15150569, 2004). "In addition, it highlights emerging challenges, including the management of polyclonal resistance, heterogeneity across KIT and PDGFRA mutations, and the need for dynamic monitoring of tumor evolution." (PMID 41517566, 2026). "Thus, FLCN‐mutated tumours with ‘hybrids’ features also show mutually exclusive IHC features, with variable combinations of CD117 (KIT) reactive eosinophilic cells, and CK7 positive clear cells, likely owing to their different cells of origin." (PMID 41384711, 2026). "The HSP90 family are molecular chaperones that regulate the stability of several proteins involved in tumor development (including KIT and PDGFRA); therefore, inhibition of HSP90 with pimitespib may represent an alternative treatment strategy to TKIs." (PMID 41264161, 2026). "In addition, GISTs are characterized by mutations in the KIT or PDGFRA genes, leading to constitutive activation of tyrosine kinase receptors, which drive uncontrolled cellular proliferation and tumor progression." (PMID 40282558, 2025). "In the non-KIT exon 11 mutation group, five out of ten patients with progression had non-gastric GISTs with a median tumor size of 116 mm (range 55.0–200.0 mm) at baseline." (PMID 40002229, 2025). "Next-generation sequencing was performed in three tumor samples, and no KIT mutations, other actionable alterations, or microsatellite instability were identified." (PMID 39858021, 2025). "In vivo therapy effect of KIT-d-MMAE and KIT-d-DM1 were studied when the tumor volume reached 80-120 mm3: mice were randomized into six groups (n = 5) and injected with DPBS, KIT-d, SMCC-DM1, KIT-d-DM1, VcMMAE or KIT-d-MMAE via tail vein twice a week for 5 times." (PMID 40963922, 2025). "Moreover, the anti-tumor efficacy and biosafety of KIT-d-MMAE were observed in several tumor models (cell line-derived xenograft, patient-derived xenograft, liver metastasis tumor model, and spontaneous tumor model)." (PMID 40963922, 2025). "Relative to the other AD samples, both AD5 and the AYA group exhibited higher expression of genes associated with aggressive tumor features and inflammation (e.g., CXCL2, TUBB3, RRM2, and MMP1) and lower expression of differentiation markers and metastatic regulators (e.g., KIT and NCAM1)." (PMID 41374320, 2025). "Indeed, lenvatinib acts by inhibiting multiple receptor tyrosine kinases, including VEGFR1–3, FGFR1–4, PDGFRα, RET and KIT, thereby impairing angiogenesis and tumor proliferation." (PMID 40507289, 2025). "Additionally, the tumor-suppressive effects of KIT-d-MMAE and KIT-d-DM1 were distinctly superior to those of VcMMAE and SMCC-DM1, respectively, indicating that conjugation with the aptamer KIT-d enhances the targeted drug delivery efficacy." (PMID 40963922, 2025). "Patients with KIT-mutant tumours had a worse prognosis, those with gastric primaries did better." (PMID 38840030, 2025). "The NCR does not capture some clinicopathologic information specific to GIST, including tumor–node–metastasis stage, risk classification of resected GIST, genetic mutations of KIT and PDGFRA, specific drug names and doses of chemotherapy, and the efficacy and safety of each treatment." (PMID 40673479, 2025). "Moreover, the mutation status of GISTs was shown to influence the tumour microenvironment, as PDGFRA-mutant GISTs reveal a specific immune profile that differs from GISTs with other mutations such as c-KIT." (PMID 41373613, 2025). "The one group consists of patients with GIST not harboring a drug-sensitive mutation, so-called quadruple wildtype tumor (q-wt, i.e. no KIT, PDGFRα, BRAF or SDH mutation)." (PMID 40044980, 2025).
tumor (continued). "Similarly, in GISTs, circulating KIT+ exosomes are elevated in metastatic patients, enhancing tumor metastasis and correlating with tumor burden." (PMID 41168571, 2025). "Moreover, the therapeutic efficacy of immunotherapy in patients with KIT-mutated GIST falls short of expectations, despite the presence of abundant tumor-infiltrating immune cells in GIST patients." (PMID 39996868, 2025). "Their effect on tumor growth, recurrence, and metastasis after radical cancer surgery in our study may be relative to their multiple targets or effects in addition to the KIT." (PMID 39744440, 2025). "Next, we combined these 3 variables that resulted in an independent association with GIST genotype (SUVmax ≤5.75, gastric location, and tumor size >10 cm) in a clinical score to enhance their accuracy in discriminating PDGFRA-mutant from KIT exon 11–mutant GISTs, assigning 1 point to each of them." (PMID 39853981, 2025). "Preclinical models support the hypothesis that KIT inhibition may enhance T-cell or NK-cell activity and modulate the tumor microenvironment, though whether this translates clinically remains to be proven." (PMID 41301010, 2025). "We further evaluated the in vivo tumor regression efficacy of orally and SC administered ANA in a patient-derived gastrointestinal stromal xenograft mouse model – UZLX-GIST2B – characterized by a KIT exon 9 driver mutation." (PMID 39930717, 2025). "However, KIT-d-MMAE showed greater tumor inhibitory activity than DS-6157a, highlighting its promise as a targeted therapeutic candidate for GIST." (PMID 40963922, 2025). "Among the seven patients with a KIT-exon 11 mutation who progressed, five had non-gastric GISTs (located in the small bowel, rectum, or duodenum) with a median tumor size of 158 mm (range 53.0–250.0 mm) prior to the initiation of imatinib therapy." (PMID 40002229, 2025). "The amplification of chromosomal regions containing the genes EGFR, MET, KIT, and PDGFRA is associated with the receptor tyrosine kinase (RTK) and growth-factor receptors, often driving proliferative and angiogenic signalling in tumours." (PMID 41573648, 2025). "Tumors expressing the KIT F436S mutant form may have reduced migration, resulting in slower tumor metastasis and invasion than those expressing the gain-functioning mutant of KIT." (PMID 40427321, 2025). "Data suggest that there is a benefit for a larger dose for those patients whose tumours have an exon 9 variant in KIT, though this is not currently recommended by NICE [IIA]." (PMID 38840030, 2025). "Ruptured GISTs were more frequently non-gastric compared with non-ruptured tumours, and they harboured more frequently KIT exon 9 mutations." (PMID 38862742, 2024). "Variations were observed in the presence or absence of ITD mutations in KIT exon 8 among the tumours." (PMID 39177283, 2024). "Also, exosomal miR-21 regulates the invasion and metastasis of tumors by targeting multiple tumor/metastasis suppressor genes in recipient cells, while miR-221/222 promotes angiogenesis in recipient endothelial cells by downregulating c-KIT, p27, and TIMP3." (PMID 39409003, 2024). "We also found mutation only in the tumor tissue in the genes DICER, ESR1, KIT, PDGFRA, and RAF1." (PMID 38565739, 2024). "Therefore, the wild-type genetic status for both KIT and PDGFRA was included as a required tumor parameter in the INT2GRATE|HPPGL Variant Evidence Framework." (PMID 38473309, 2024). "Similarly, we identify mutations in both tumor-suppressor genes, e.g., ABL1, JAK2, MAP2K1, and KIT, from poor responders in CML, suggesting that these are two of the key mechanisms by which tumor cells evolve to acquire drug resistance." (PMID 38459554, 2024). "Imatinib achieves its tumor-killing effect by inhibiting IDO1 expression through the KIT pathway." (PMID 38443340, 2024). "On this basis, we proposed that the KIT- cells may be normal fibroblasts, while the KIT+ ones were all tumor cells." (PMID 38443340, 2024).
tumor (continued). "Six patients were alive and progression free at 6 months (local radiology review, 25%); 5/26 (19%) had objective response at 12 weeks; median OS was 7.7 months; ddPCR assay correctly identifies KIT alterations in circulating tumor DNA (ctDNA) in 16/17 patients." (PMID 38417447, 2024). "Additionally, examination of tumor tissues from KITV558A/WT mice and KITV558A/WT/ZSWIM4−/− mice by qRT-PCR and western blot showed that loss of ZSWIM4 expression increases KIT and BMAL1 expression." (PMID 38951864, 2024). "This analysis revealed a loss of the immune-related molecule CCL2 over time, contributing to a “cold” tumor microenvironment, and an increase in metastasis-associated molecules like MITF, KIT, and VIM, suggesting a potential transition to a mesenchymal phenotype." (PMID 38975339, 2024). "Secondary KIT mutations (c.998G>C and c.2383G>C), which were not initially detected in tumour cells at diagnosis, were identified after the development of resistance to toceranib." (PMID 39177283, 2024). "Notably, majority targets of TB-2 are implicated in tumor therapy, including TGM2, KIT, EGFR, AURKA, FASN, and CDK2, which have garnered extensive research attention." (PMID 39376614, 2024). "However, GISTs can acquire drug-resistant secondary mutations in KIT or activate alternative signaling pathways to circumvent the inhibition of KIT after the initial response to imatinib, leading to tumor relapse." (PMID 38951864, 2024). "In addition, two variants of uncertain biologic significance were discovered in KIT (missense, p.K492R) and HRAS (nonsense, p.Q70*) as passenger mutations in a tumour (case 22M) with a concomitant NRAS mutation." (PMID 36416305, 2023). "Three of the five tumours with exon 11 mutations were also tested for KIT exon 9 mutations; none had a mutation in line with the mutually exclusive nature of exon 11 and exon 9 KIT mutations in GIST." (PMID 37545902, 2023). "The authors conclude that expression of SPRY4 and KIT may represent markers of tumor progression and could be predictive of imatinib therapeutic response." (PMID 37197427, 2023). "(ii) Receptor tyrosine kinases (RTK): The activation of RTKs, such as EGFR, ERBB2, KIT, and PDGFR, by mutation or translocation directly leads to tumor growth and is a clear therapeutic target; these mutations were detected in 216 of 1003 cases or around 20% of the cases." (PMID 36251535, 2023). "KIT was reduced in TC samples and lower in tumor cells than those in normal cells." (PMID 37506147, 2023). "Firstly, the main limitation is that SEER database has shortcomings in information depth, lacking several important factors such as intraabdominal tumor rupture, margin status, and genetic mutation of KIT or PDGFRA." (PMID 37855869, 2023). "Pazopanib is an oral multi-targeted tyrosine kinase inhibitor that directly targets receptor tyrosine kinases (RTKs), vascular endothelial growth factor (VEGFR) 1/2/3, platelet-derived growth factor (PDGFR) α/β and KIT, thereby blocking tumour growth and inhibiting angiogenesis." (PMID 37400856, 2023). "Furthermore, we developed and validated a combined model that incorporated Radscore and maximum diameter of the tumor, tumor margin, AVT, which exhibited high accuracy for preoperatively predicting KIT exon 11 mutation." (PMID 37645430, 2023). "ITDs in c-kit exon 11 were found in tumours that generally had a higher Patnaik (p = 0.002) and Kiupel (p < 0.001) grading, a higher mitotic count (p < 0.001), an increased number of Ki67-positive cells (p = 0.006), and an aberrant KIT pattern (p = 0.018)." (PMID 37238124, 2023). "In addition, in vivo studies have demonstrated enhanced immune responses, including increased T‐cell activation, natural killer cell clonal expansion, and enhanced tumor antigen presentation with KIT inhibitors." (PMID 37403699, 2023). "Furthermore, data showed that tumours with an ITD in c-kit exon 11 tended to have an aberrant KIT pattern (p = 0.018)." (PMID 37238124, 2023).
tumor (continued). "Immunohistochemical studies on both tumours showed KIT and DOG-1 positivity, with SDHB retained." (PMID 37663588, 2023). "For instance, elevating KITLG expression in fibroblasts and endothelial cells could stimulate MC activation and proliferation through the KITLG/KIT pathway, thereby inhibiting tumor cells and enhancing patient outcomes." (PMID 38031173, 2023). "In 15 out of 38 plasmas from GIST patients harboring c-KIT or PDGFRA mutations in tumor tissues, Maier and colleagues identified ctDNA (circulating tumor DNA) bringing tumor-specific mutations, by the allele-specific Taq-Man duplex PCR allele-specific ligation PCR technique." (PMID 37046997, 2023). "Simultaneously, the different KIT exon 11 mutations such as point mutations, compound mutations and deletion mutations were not different based on gender, age, tumor location, CD117, CD34, DOG-1, bleeding or necrosis." (PMID 37901323, 2023). "This is the case for primary and secondary KIT mutations which have been found in plasma from GIST patients and for the extracellular domain of soluble KIT, which is a faithful biomarker of tumor outcome in patients treated with sunitinib after acquired imatinib resistance." (PMID 37046997, 2023). "Interestingly enough, in this study, the expression of c-KIT in adenocarcinoma was higher than in SCC, perhaps associated with innate tumor malignancy and aggressiveness." (PMID 36851392, 2023). "NGS analysis of her GIST lesion revealed a quadruple wild-type tumor (no mutations in c-KIT, PDGFRA, SDH, RAS-P [RAS, BRAF, NF-1]) with a FGFR3 p.G145S mutation/variant which is of a germline rather than somatic variation." (PMID 35885469, 2022). "In case 13, a second c-KIT mutation p.N822K was detected in the current specimen but not in the previous one, indicating a tumor progression with imatinib resistance and an interval change (43 months)." (PMID 35885469, 2022). "As a neoplasm involving the HSC compartment, the KIT D816V (and other KIT) mutations can be found in both neoplastic MCs and CD34+ BM HSC, as well as in other myeloids (e.g., neutrophils, monocytes, basophils and/or eosinophils) and/or lymphoid (e.g., T and B lymphocytes) cells." (PMID 35626091, 2022). "In patients with metastatic progressive KIT-mutant GIST, tumor burden was higher with detectable KIT ctDNA mutation than in those without (median, 5.97 cm vs. 2.40 cm, p = 0.0195)." (PMID 35273917, 2022). "Moreover, decreased KIT expression reduces angiogenesis in mouse models of ocular pathology and tumour growth." (PMID 35416527, 2022). "Interestingly, the highest expression of KIT was found in tumor areas directly adjacent to the tumor stroma." (PMID 35842424, 2022). "Tumor tissue samples were submitted for histological diagnosis, grading and KIT immunostaining." (PMID 35159380, 2022). "In addition to the contributory role exerted by cancer cell-intrinsic expression and activation of c-KIT in tumor development and progression, several lines of evidence suggest a key role for SCF-c-KIT signaling occurring in the tumor microenvironment." (PMID 35490363, 2022). "Tumor volume did not correlate with ctDNA concentrations or detection of known primary KIT mutations." (PMID 36428589, 2022). "While MCs derived ex vivo have a finite lifespan without SCF, they are also capable of autocrine SCF secretion and activation of KIT which may account for the prolonged anti-tumor effect observed with only a single injection." (PMID 35574362, 2022). "Additionally, neutrophils are able to adapt an oxidative phenotype through c-KIT signaling in response to tumor." (PMID 35251008, 2022). "The mutation analysis revealed a variety of changes in the KIT tumor genotype during treatment that were heterogeneous with no specific mutation pattern or association with outcome (OS) or tumor growth rate." (PMID 35050442, 2022).